EPCAM (epithelial cell adhesion molecule)
Diseases named in the same sentence as EPCAM in open-access papers (continued):
Sharing a sentence is not in itself a finding about the gene and the disease.
tumor (continued). "The present study showed that combination of EpCAM/CD3 BsAb and MUC-1/CD3 BsAb could dramatically enhance elicited CTL response, as well as promote cytokine production in tumor cell lines and primary tumor cells." (PMID 34522164, 2021). "The ectodomain of EpCAM and CTSL are both secreted into the tumor micro-environment of cancer patients, whereby EpCAM could possibly inhibit CTSL activity." (PMID 34209658, 2021). "Hence, combination therapy with EpCAM/CD3 BsAb and MUC-1/CD3 BsAb was expected to be a promising strategy to enhance the anti-tumor efficacy." (PMID 34522164, 2021). "Interestingly, on IF staining, the expression of CSC markers YAP1 and EpCAM was preserved in GA0825 PDX, recapitulating the expression in the corresponding donor PC cells (IP-116) and its primary tumor." (PMID 34162421, 2021). "Here, we demonstrate the potential role of BMP9 and its target transcription factor inhibitor of DNA‐binding protein 1 (ID1) in the activation of EpCAM+ CSC properties in HCC, and we demonstrate the effect of BMP receptor inhibitors, which suppress HCC tumor growth by inhibiting BMP9‐ID1 signaling." (PMID 33834612, 2021). "All together we demonstrated that the EpCAM-specific cytotoxicity of anti-EpCAM CAR-expressing iNK cells against tumour cell lines, with tolerance towards autologous normal cells and little on-target off-tumour effects." (PMID 34802459, 2021). "We observed both tumor cells (EpCAM+) and M2 macrophages (CD11b+) positive for oHSV-1 (GFP+), producing active PD-L1 BiTE and mediating significant increase in number of CD3+ cells but decrease in tumor and M2-like macrophages." (PMID 33820820, 2021). "As shown in a representative manner for patient #6, PD-L1, EGFR and EpCAM were expressed to a lower degree or on subsets of tumor cells while FAP expression was absent." (PMID 34484225, 2021). "The non-residualizing [125I]I-HPEM label provided the highest tumor-to-muscle and tumor-to-bone ratios and is more suitable for EpCAM imaging in early-stage PCa." (PMID 34298801, 2021). "Interestingly, both EpCAM and CTSL are known to be secreted into the tumor microenvironment and are present in the serum of human cancer patients." (PMID 33980181, 2021). "Multi-parametric immunofluorescence showed variable αV levels with a mean of 51 ± 7% of EpCAM+E-cadherin+ tumour cells that expressed the integrin, while only 21 ± 6% of non-epithelial EpCAMnegE-cadherinneg cells were αV+." (PMID 34471106, 2021). "The healthy control slides were negative for the tumour markers (CK/EpCAM, PAX8 and vimentin), but a few WBCs showed co-expression of PD-L1 and CD16/45." (PMID 34944844, 2021). "While only 3 of 10 mice injected with untreated EpCAM−/CD133− nonstem cells exhibited a tumor formation, the tumor incidence was 7 out of 10 for the mice injected with Dox‐treated EpCAM−/CD133− nonstem cells." (PMID 33524223, 2021). "The CAR-expressing iNK cells exhibited the antigen-dependent cytotoxicity against EpCAM-positive tumours cells, but not against EpCAM-positive normal cells, demonstrating to be a safe CAR-effector cell source for immunotherapy against cancer." (PMID 34802459, 2021). "The number of EpCAM-positive tumor cells dropped from 23 to 0, 14 days after the last instillation and follow-up samples were still negative for tumor cells until day 701 with the exception of day 631 where one tumor cell was found." (PMID 33837852, 2021). "In contrast, Western blotting and tissue immunostaining showed that levels of phospho-Rb (Ser807/811) were frequently high in non-responders, which also displayed intense EpCAM staining in tumor cells that was not altered after irradiation." (PMID 33767581, 2021). "EpCAM is a surface marker commonly used to detect CTCs, since it is present in tumor cells derived from human epithelial tumors, but absent in blood cells." (PMID 33925308, 2021).
tumor (continued). "Positive and negative magnetophoretic isolation is possible with tumor cells expressing epithelial cell adhesion molecule (EpCAM) as the most widely used antigen for positive selection and anti-CD45 for the depletion of white blood cells as a negative marker." (PMID 34439219, 2021). "Tumor # 2 showed a faint expression of mCherry, but not significant, thus suggesting EpCAM+ cells (copGFP) dominated tumor growth within the tumor microenvironment over EpCAM- non-CSCs (mCherry)." (PMID 32547703, 2020). "EpCAM-positive HCC cells display some of the liver cancer stem cell-like characters which include; self-renewal and differentiation, maintaining the capacity for malignant proliferation, invasion, metastasis, and tumor recurrence." (PMID 32212818, 2020). "Lentiviral vectors have been broadly used to generate NK cells expressing CARs with 1st, 2nd and 3rd generation designs which target different tumor antigens including CD19, CD20, TF in TNBC, CD33, CD7, CD22, ErbB2, EpCAM, Glypian-3 (GPC3), CS1, EGFR, B cell maturation antigen (BCMA) and CD4." (PMID 32707982, 2020). "EpCAM was able to correctly identify all primary debulking tumor-negative and tumor-positive lymph nodes, with a sensitivity, specificity, PPV, NPV and AUC of 88%, 100%, 100%, 94% and 0.97 (95% CI 0.90–1.00), respectively." (PMID 32545676, 2020). "Moreover, IF staining showed that the tumor stem cell markers CD133 and EpCAM were both highly expressed in recurrent samples compared with the expression in initial tumors (CD133+: 19 vs. 5%, p = 0.002; EpCAM+:15 vs. 6%, p = 0.005)." (PMID 32983980, 2020). "It has been shown that CD326, also known as the epithelial cell adhesion molecule, could form a protein complex with β-catenin for promoting CSC/CIC properties essential for tumor progression, recurrence, and metastasis." (PMID 32102440, 2020). "Therefore, we aimed to determine the spatial heterogeneity of CSC-features by the intensity and proportion of EpCAM-positive cell-populations within different locations of HCC-nodules, and to determine its impact on recurrence and aggressive tumor behaviour." (PMID 33225916, 2020). "To capture a wide variety of CTCs including tumor cells without EpCAM expression, we have developed a novel microfluidic system (“universal CTC-chip system”) in which any antibody to capture CTCs is easily conjugated." (PMID 32260559, 2020). "Circulating tumor cells can be positively isolated based on EpCAM overexpression, however minimizing non-specific cell-capture remains a prudent challenge." (PMID 32561829, 2020). "These antigens are overexpressed by tumor cells but also shared with normal tissue (eg, carcinoembryonic antigen (CEA), epithelial cell adhesion molecule (Ep-CAM), mucin-1 (MUC-1), melanoma antigen recognized by T cells-1 (MART-1/Melan-A), glycoprotein 100 (gp100), and tyrosinase (Tyr))." (PMID 33268350, 2020). "Furthermore, the specific tumor cell marker, HER2, was detected in both CSV and EpCAM‐enriched CTCs, which was consistent with IHC results." (PMID 31981446, 2020). "Furthermore, consistent with our in vitro studies, when we stained tumor sections from the mice injected with EpCAM−/CD133− cells overexpressing KLF4, these tumor sections had increased levels of both the KLF4 and EpCAM proteins." (PMID 32408542, 2020). "The oncolytic group B adenovirus EnAdenotucirev (EnAdV) was modified by Freedman and colleagues to express another BiTE coordinately binding EpCAM+ tumor cells and CD3+ T cells, leading to clustering and activation of both CD4+ and CD8+ T cells with tumor cells." (PMID 32664210, 2020). "For the first time, we demonstrate that, without genetic alteration, high levels of EpCAM expression on Hep3B cells possess unique tumor-initiating capability in the liver microenvironment, and thus possibly contribute distinctly to tumorigenesis." (PMID 32547703, 2020).
tumor (continued). "The mixed group’s tumors were of the highest interest for us, because these tumors were initiated from a 50/50 mixture of copGFP-expressing EpCAM+ CSCs and mCherry-expressing EpCAM- non-CSCs (Hepa1-6 cells) to track the tumor lineage in vivo." (PMID 32547703, 2020). "In this study, tumour-derived EpCAM was heavily glycosylated while EpCAM derived from autologous thyroid was not or weakly N-glycosylated." (PMID 32046162, 2020). "Moreover, cells expressing both the EpCAM and CD133 surface markers were shown to possess more characteristics of LCSCs in HuH7 cells and exhibit a higher tumor initiating ability." (PMID 32408542, 2020). "EPCAM (epithelial cell adhesion molecule) is frequently used as a marker of circulating tumor cells but it has not been evaluated in patients’ urine yet." (PMID 32630458, 2020). "Taken together, we have shown that the tumor-initiation capabilities of HepG2 cells were not significantly affected by EpCAM expression in vivo in an orthotopic liver microenvironment." (PMID 32547703, 2020). "Marker-based CTC-tests can also lead to false-positive-results, as many tumor-markers can be expressed on non-pathological cells, including EPCAM and other markers." (PMID 32391268, 2020). "The experimental setting for the combinatorial approach comprises on the one hand a bispecific antibody directed against EpCAM and CD3, thus retargeting T cells to tumor cells, inducing initial T cell stimulation in a tumor cell-directed, but MHC-independent manner." (PMID 32504247, 2020). "Primary sorted CD44+/EPCAM+ cells derived from a 74-year-old male patient, who underwent surgery for stage IIIA NSCLC, were cultured to assess the growth ability of these cells to form tumor spheres in vitro." (PMID 32391123, 2020). "The cytology-based ISET®-CTC-test is independent of the presence of any tumor-surface-markers on cancer cells, such as the Epithelial-Cell-Adhesion-Molecule (EpCAM) markers, used by most other CTC technologies." (PMID 32391268, 2020). "Also, PTC cells with DOCK9-AS2 knockdown presented restrained tumor sphere forming efficiency and lowered levels of stemness-related proteins including CD133, Nanog, OCT4, SOX2, EpCAM, and ALDH1A1." (PMID 32917852, 2020). "Tumor growth was monitored using non-invasive ultrasound imaging, and the tumor nodule was detected on Day 35 in the EpCAM-High group (data not shown)." (PMID 32547703, 2020). "EpCAM, selected as a standard epithelial tumor cell marker, was found to be weakly or not expressed in cells and exosomes from ccRCC cell lines in contrast to the control cell line MCF7." (PMID 33276608, 2020). "Levels of CD90 (THY1), CD133 and EpCAM mRNA were measured in tumor tissues from 13 patients with DPHCC and 34 patients with non- DPHCC subtypes." (PMID 32231746, 2020). "However, using positive immunomagnetic selection targeting EpCAM, HER2, and EGFR improved and optimized the enrichment of tumor stem cell and EMT like CTC compared to cell capturing with anti-EpCAM alone in different tumor entities." (PMID 33014830, 2020). "Unlike Hep3B, the HepG2 experiment failed to exhibit differences in tumor volume or liver weight between EpCAM-High and EpCAM-Low groups." (PMID 32547703, 2020). "Immunohistochemistry (IHC) showed that, in CDX and two PTs, tumor cells were positive for EpCAM and CK8/18 and negative for CK7 and vimentin." (PMID 32313004, 2020). "Both miR-200c from total serum exosomes and EpCAM-positive serum exosomes in combination with CA-19.9 enhanced the tumor marker’s ability to distinguish between PDAC and non-PDAC." (PMID 31941049, 2020). "Primary cultures of EpCam+ tumor cells from the patient with no stemness gene amplifications had relatively low proliferative activity." (PMID 32523653, 2020). "In contrast to EpCAM, CA9, CD70, and CD147 could represent promising markers to identify tumor-specific EVs in ccRCC." (PMID 33276608, 2020).
tumor (continued). "Dormant tumor cells from the liver were recovered only from the FAC/AIT group 2–3 months after culture ex vivo (FAC/AIT L) and showed similar characteristics as MMC for the expression of neu, EpCAM, or predominant CD24+CD44+ fraction." (PMID 33115528, 2020). "Accordingly, our in vivo xenograft studies demonstrated that with KLF4 overexpression, EpCAM−/CD133− non-stem cells attained an in vivo tumor-forming ability comparable to EpCAM+/CD133+ LCSCs." (PMID 32408542, 2020). "The lack of expression of EPCAM in neoplasms from EPCAM 3′-end carriers will be more significant as the more intense and robust the expression is in its normal tissue." (PMID 33003511, 2020). "As EpCAM is weakly expressed on exosomes and heterogeneously expressed in both tumors and normal tissues, it is not suitable for tumor detection using exosomes." (PMID 33276608, 2020). "EpCAM is widely used as a biomarker in sensing devices, since EpCAM is usually expressed in circulating tumor cells (CTCs) but not in healthy hematological cells." (PMID 32295170, 2020). "HCC with heterogeneous EpCAM-expression had characteristics remarkably similar to HCC without any EpCAM-positive tumor cells." (PMID 33225916, 2020). "In the mice with steatohepatitis, EpCAM+ CSCs have shown significantly increased ability in terms of tumor initiation and growth, compared to that with EpCAM- non-CSCs inoculation (p < 0.005)." (PMID 32547703, 2020). "Mesenchymal CD44+/CD24−/low CSCs do not express E-cadherin but gain further tumor initiating capacity with the expression of the epithelial adhesion molecule EpCAM that marks “hybrid E/M” states." (PMID 32760736, 2020). "Double immunofluorescent staining showed that the apoptotic cells were mainly from EpCam+ tumour cells, not from CD45+ immune cells." (PMID 32732922, 2020). "Absence of tumor and copGFP/EpCAM expression in the EpCAM-Low group suggests that Hep3B cells with lower EpCAM expression do not carry tumor-initiation capability in vivo." (PMID 32547703, 2020). "Although EpCAM and FRα meet the criteria of a suitable molecular target, high expression was observed in epithelial cells in tumor-negative fallopian tubes and endometrial cells of the uterus." (PMID 32545676, 2020). "Adecatumumab did not induce measurable tumor regression; however, patients treated with high-dose antibody and expressing high levels of EpCAM retrospectively showed reduced development of new metastases (3/18 versus 14/29 patients)." (PMID 32507912, 2020). "At the time point of 2 days after the seeding, the CD44+/EPCAM+ cells had formed non-adherent spheres in culture, and more than 50% of these tumor spheres were either small or medium in size, with a total area below 16.000 μm2." (PMID 32391123, 2020). "Thirty-three patients (47.8%) contained tumor spots with and without EpCAM-expression of diverse quality, confirming the presence of spatial heterogeneity of CSC-features in nearly half of patients with HCC (E−/+)." (PMID 33225916, 2020). "Additionally, we found that the tumor stem cell markers (CD133 and EpCAM) were both highly expressed in recurrent HCCs compared with initial HCCs (CD133+: 19 vs. 5%, p = 0.002; EpCAM+: 15 vs. 6%, p = 0.005)." (PMID 32983980, 2020). "Despite its origin, one of the tumor samples was EpCAM negative and was therefore not included in the analysis." (PMID 32630661, 2020). "Given the great interest in therapeutic immunomodulation and targeting of tumor cells with autologous lymphocytes genetically manipulated to express an scFv-based chimeric antigen T cell receptor, CAR-T cells were tested with our panel of three EpCAM binders." (PMID 33127646, 2020).
tumor (continued). "Apparently, the EpCam+CD44lowCD24– phenotype represents a subpopulation of progenitor tumor cells that are capable of non-CSC to CSC plasticity, and further studies are needed to assess their importance in metastasis based on clinical data." (PMID 32523653, 2020). "Hence, in the present study, we used epithelial cells isolated directly from dissociated tumors and from the respective adjacent non-tumor colon tissues of CRC patients, based on their surface EpCAM (CD326) antigen expression." (PMID 31999740, 2020). "Here, we consistently detected the highest protein levels for the PD-L1 protein in EpCAM-negative/keratin-weakly positive tumor cells with mesenchymal attributes." (PMID 32466213, 2020). "Furthermore, soluble CD44, CD44v6, CD44v8-10 and EpCAM were significantly increased in the recurrence group for early stage CCA; they also correlated with high levels of the tumor marker CA19-9." (PMID 32039729, 2020). "Our results indicate that the CEP-LP@S/D co-delivery system could enhance the accumulation of drugs in the tumor tissues and target CSCs via the specific peptide recognition receptors CD133 and EpCAM, which are over-expressed on these cells." (PMID 32850663, 2020). "EpCAM-negative tumor nodules demonstrated similar low aggressiveness in tumor features like EpCAM-heterogeneous tumor nodules." (PMID 33225916, 2020). "Using TMAs constructed with different normal and neoplastic tissues, we observed that EPCAM expression in neoplasms reflected the expression of its normal counterpart." (PMID 33003511, 2020). "EpCAM, αvβ6 and FRα were detected on the epithelial cells of tumor-negative fallopian tubes, the endometrium and ovarian inclusion cysts, although EpCAM with lower intensities." (PMID 32545676, 2020). "A partial loss of EPCAM staining in CRC was described in poorly differentiated carcinomas and/or at the invasive tumor front as an independent poor prognostic factor in nondeficient MMR CRC." (PMID 33003511, 2020). "By contrast, OCM.87 was positive for PAX8, EpCAM and CA125 and thus confirmed as a tumour model." (PMID 32054838, 2020). "Cancer stem cells (CSCs) are more generally characterized as cellular subset that maintains tumor growth, such CSCs are recognized by the expression of extracellular markers like CD 24, CD44, CD133, epithelial cell adhesion molecule (EpCAM) etc. in liver malignancies." (PMID 31921870, 2019). "In addition, EpCAM, CD44, and CD24 have been reported to be relevant for tumor progression and metastatic processes." (PMID 31261643, 2019). "Nevertheless, to better understand and monitor tumor cell dissemination, the identification of transcription factors or of microRNAs that govern EPCAM gene expression and that are implied in Epithelial-Mesenchymal Transition (EMT) is of high interest in the context of tumor diagnosis." (PMID 31225512, 2019). "Considering the higher expression of chemokines, including CCR5 and CCR6, which might attract EpCAM+ CD4+ T cells to the tumor sites, we determine whether EpCAM+ CD4+ T cells are present in the tumor microenvironment within CC patients using light microscopy." (PMID 31354723, 2019). "To date, however, only the CellSearch System—using microbeads magnetically labeled with epithelial cell adhesion molecule antibodies (anti-EpCAM)—has been approved by the US Food and Drug Administration (FDA) for the enrichment of circulating tumor cells (CTCs) during liquid biopsies." (PMID 30782169, 2019). "EV EpCAM signal did not further increase at the subsequent time point, perhaps due to the modest increase in tumor volume in this interval." (PMID 31921310, 2019). "EPCAM and TSPAN8 showed inconsistent trend in ATC tissues, which may result from the heterogeneity between cell line data and tumor tissue data." (PMID 31183379, 2019). "Examples of tumor target antigens include CD19, EpCAM, Her2/neu, EGFR, CEA, and more." (PMID 31488104, 2019).